TEX36 (testis expressed 36)
Synonyms: C10orf122; bA383C5.1
Tractability: No criterion of Open Targets' tractability assessment is met for any kind of drug.
Gene: Protein-coding gene on chromosome 10 (125,576,522 to 125,683,163, reverse strand). Ensembl gene ENSG00000175018.
Subcellular location (Human Protein Atlas): Vesicles; Cytosol
Genetic constraint (gnomAD): Loss-of-function variants: 12 observed, 14.7 expected, observed/expected ratio (o/e) 0.82, 90% interval 0.52 to 1.32. The upper end of that interval is the gene's LOEUF score, 1.32, which puts it in group 5 of 6, group 1 being the genes least tolerant of losing a copy. Missense variants: 224 observed, 237.56 expected, observed/expected ratio (o/e) 0.94, 90% interval 0.85 to 1.05. Synonymous variants: 93 observed, 88.02 expected, observed/expected ratio (o/e) 1.06, 90% interval 0.89 to 1.25.
Homologues: Orthologues: chimpanzee TEX36 (99% identical), macaque TEX36 (90% identical), dog TEX36 (80% identical), pig TEX36 (76% identical), rabbit TEX36 (75% identical), rat Tex36 (64% identical), guinea pig TEX36 (63% identical), mouse Tex36 (61% identical).
Diseases named in the same sentence as TEX36 in open-access papers:
TEX36 is named in the same sentence as 1 disease in open-access papers, as found by Europe PMC text mining. Sharing a sentence is not in itself a finding about the gene and the disease.
TEX36 shares sentences with these, for which no sentence is quoted: copy number variation (1 paper).